PTH (parathyroid hormone)
Diseases named in the same sentence as PTH in open-access papers (continued):
Sharing a sentence is not in itself a finding about the gene and the disease.
hypovitaminosis D (continued). "Radiological signs of rickets may be mild or even lacking, as prolonged periods of elevated PTH levels are required before they manifest in early infancy." (PMID 34910242, 2022). "Vitamin D deficiency or hereditary factors resulting in changes of 1,25(OH)2D, PTH, and FGF23 levels could cause genetic or non-hereditary rickets." (PMID 33015068, 2020). "Lack of clinical improvement (rickets resolution) following vitamin-D supplementation in our patient may be explained by the deleterious effect of persistently elevated PTH on chondrocytes and bone." (PMID 24379038, 2013). "Unlike rickets there is no compensatory rise in 1,25(OH)2D and this may be due to persistent low serum parathyroid hormone (PTH) concentrations." (PMID 24358815, 2012). "Levels of 25-vitamin D were lower and the prevalence of hypovitaminosis D using assay 1 was higher than using assay 2 in patients with CKD, regardless of similar levels of calcium, phosphate, and parathyroid hormone." (PMID 31769778, 2020). "Our data support the hypothesis that the high levels of PTH found in girls with CPP do not represent, as it is commonly assumed, an increase secondary to hypovitaminosis D." (PMID 35750999, 2022). "Parameters such as parathyroid hormone (PTH), alkaline phosphatase (ALP), ionized calcium, phosphorus, magnesium, and vitamin D may be normal or only slightly affected in a prematurely born infant who has osteopenia with or without signs of rickets at several weeks old." (PMID 30566429, 2018).
Obesity (156 papers, 2002 to 2026). Accumulation of substantial excess body fat. "According to the first consensus meeting, diagnostic criteria include PTH resistance, ectopic ossifications, early-onset obesity with TSH resistance, family history, and features of AHO." (PMID 41170251, 2025). "Obesity has been linked to decreased serum levels of 25-hydroxyvitamin D and increased serum levels of PTH." (PMID 40585599, 2025). "A causative relation between low 25-OH-D3 and elevation of PTH in patients with obesity is still a matter of discussion." (PMID 38750418, 2024). "We describe a new missense GNAS variant, c.791A > C, p.(Asp264Thr), in a family with obesity, hyperphagia and mild PTH resistance." (PMID 39104441, 2024). "Obesity is associated with higher serum parathyroid hormone (PTH) levels derived from increased vitamin D deposition in adipose tissue." (PMID 38075210, 2023). "A study conducted in adolescent girls with obesity showed that the ratio of PTH to vitamin D was negatively associated with measures of glucose homeostasis and positively associated with inflammatory markers." (PMID 36291463, 2022). "Nonetheless, this class of obesity, when associated with the Metabolically Unhealthy Phenotype, presented a higher risk of alterations to PTH, Calcium, Vitamin D, and Phosphorus, thus favoring the emergence of metabolic bone diseases." (PMID 31489911, 2019). "Some plausible factors include: behavioral (e.g., physical activity, diet, sun exposure, etc.), molecular (e.g., calcium, parathyroid hormone or PTH, etc.), clinical (e.g., obesity vs. weight loss), or physiological (e.g., skin pigmentation, genetics)." (PMID 30044889, 2018). "Obese young Finnish adults exhibited lower total and measured 25(OH)DFree and slightly higher PTH than their normal-weight peers, and 25(OH)DFree was associated with obesity-related parameters." (PMID 29489840, 2018). "The PTH levels showed a significant positive association with BMI, WC and the WC component of MetS, suggesting a possible role in the pathophysiology of obesity." (PMID 29149839, 2017). "Elevated concentrations of serum PTH are associated with numerous adverse health outcomes and commonly coincide with obesity." (PMID 28272298, 2017). "Obesity is associated with increased expression of PTH, duodenal 5-HT, IL-6, AGEs and THF-α, as well as decreased expression of BMP, IGF, Activin/TGF-β, Wnt, brain 5-HT, estrogen and EPCs." (PMID 27746742, 2016). "The VDR gene polymorphisms have been shown to be associated with obesity, insulin resistance, serum levels of testosterone, Luteinizing hormone, PTH, and 25 (OH) D." (PMID 27141540, 2015). "In the present study, we examined the relationship between serum levels of 25-hydroxyvitamin D (25[OH] D), Parathyroid Hormone (PTH), obesity and selected cardiovascular disease risk factors in Saudi subjects." (PMID 24524260, 2014). "Serum levels of 25OHD3 were inversely associated with obesity, being born outside Sweden and with serum levels of PTH." (PMID 23945218, 2013). "In summary, adult Saudi patients with subclinical hypothyroid dysfunction harbor several cardiometabolic abnormalities, including obesity and dyslipidemia, the latter being associated positively with PTH levels." (PMID 23962199, 2013). "Early, smaller studies reported an association between obesity and low serum 25D concentrations, as well as high concentrations of parathyroid hormone (PTH) and 1,25-dihydroxyvitamin D (1,25D)." (PMID 23519290, 2013). "In this context, the aim of our study was to evaluate the associations between 25(OH)D or PTH concentrations and the risk of obesity, and MetS and its individual components in a large sample of individuals with a wide range of adiposity." (PMID 23228198, 2012). "Maternal inheritance of an inactivating GNAS mutation results in AHO with additional features of obesity and resistance to a variety of hormones, including parathyroid hormone (PTH)." (PMID 23284784, 2012).
Obesity (continued). "AHO is typically associated with dysmorphic “moon” facies, obesity, short stature, brachydactyly, and end-organ resistance to parathyroid hormone." (PMID 21559111, 2011). "Obesity, older age, and reduced daily intakes of calcium and vitamin D are associated with higher levels of PTH." (PMID 19187564, 2009). "Vitamin D-specific downstream targets with risk of obesity-related parameters including height, weight, BMI, 25-hydroxyvitamin D, parathyroid hormone, glycemic status, and lipid profile (TG, LDL, HDL, and TC) have provided strong clues to clarify the molecular mechanisms." (PMID 37184736, 2023). "Itwas found that an interaction between PTH and obesity was observed, suggesting alink with heart failure risk in obese individuals, although the role of PTH inthe development of heart failure was unclear and there was no relationshipbetween 25-OH vitamin D3 and heart failure." (PMID 39076268, 2023). "Importantly, some associations were lost after adjusting for visceral adipose tissue, suggesting a role of the latter in the association between PTH, vitamin D and insulin resistance in people with obesity." (PMID 36291463, 2022). "Furthermore, weight loss was accompanied by increase in serum 25(OH)D levels and decrease in serum PTH levels in both adult and pediatric cohort studies, suggesting that obesity is a modifiable risk factor of mineral disorder." (PMID 34422722, 2021). "Additionally, systemic inflammation, obesity, and PTH levels have been associated with changes in circulating vitamin D levels." (PMID 31557191, 2019). "Patients with ESRD have a higher mortality rate than general population, anemia, hypoalbuminemia, infection, lower intact parathyroid hormone level, upper gastrointestinal bleeding, obesity, and lower vitamin D are traditional risk factors for mortality in ESRD patients." (PMID 31880213, 2019). "Age, gender, PTH and obesity appear to be global risk factors for low 25(OH)D." (PMID 29273017, 2017). "In fact, mean values for PTH substantively increase as BMI (Z-score) rises: from mean values of 31.1 pg ml−1 in those individuals with normal BMI status to 45.2 pg ml−1 in those individuals with severe obesity; therefore, there appears to be a positive association between PTH and BMI (Z-score)." (PMID 28287628, 2017). "However, further, larger studies found obesity to be associated with lower 25D concentrations, high PTH concentrations and low 1,25D concentrations." (PMID 23519290, 2013). "Previous studies have also shown a positive association of PTH with obesity." (PMID 23596520, 2013). "Therefore, we expected that there is association between obesity with serum concentration of calcium, vitamin D and PTH." (PMID 23497722, 2012). "Moreover, PTH could be a novel obesity driven gene associated with MI, which needs further validation." (PMID 33842562, 2021). "Moreover, PTH could be a novel obesity driven gene associated with the pathogenesis of MI, which needs further validation." (PMID 33842562, 2021). "However, the reason for the association between obesity and lower levels of 25-hydroxy vitamin D (25(OH)D) and higher parathyroid hormone (PTH) levels is still unclear, and several hypotheses have been proposed about this relationship." (PMID 31164629, 2019). "Parathyroid hormone (PTH) has been implicated in promoting adipose tissue browning and thermogenesis, but its metabolic impact in the context of obesity remains uncertain." (PMID 42231020, 2026). "Cortisol also suppresses osteoblast function, promoting bone resorption and increasing calcium excretion, which, in combination with PTH dysregulation, worsens obesity-related bone disease." (PMID 40136609, 2025). "Elevated PTH levels in obesity drive increased renal phosphate retention, which, in turn, suppresses calcitriol synthesis, further impairing calcium absorption." (PMID 40136609, 2025).
Obesity (continued). "This aligns with the literature indicating that obesity alters VD metabolism, with elevated PTH and disrupted regulation of 1,25(OH)2D due to changes in VD-metabolizing enzymes." (PMID 39765737, 2024). "Two studies analysed longitudinal 25-OH-D3 and PTH levels in 32 German children and 67 Spanish children with obesity over 12 months." (PMID 38750418, 2024). "Longitudinal data in children with obesity with low 25-OH-D3 and documented calcium intake are necessary to define PTH thresholds that require treatment with vitamin D and/or calcium." (PMID 38750418, 2024). "Our study adds to the scarce long-term follow-up data of 25-OH-D3 levels in combination with PTH in children with obesity." (PMID 38750418, 2024). "Being consistent with prior studies, the results suggest that special attention should be paid to patients with CKD and obesity in the interpretation of PTH results." (PMID 36920734, 2023). "Children with PHP variably manifest bone defects with ectopic ossifications, short stature, and early-onset obesity, and their endocrine defects include resistance to parathyroid hormone (PTH) and thyroid stimulating hormone." (PMID 37686455, 2023). "Considerable clinical differences can be found between different types, but the main clinical features include PTH resistance, heterotopic ossification, short finger deformity, and early obesity." (PMID 36669868, 2023). "Patients present with resistance to PTH and other hormones, subcutaneous ossifications, brachydactyly, short stature, and early-onset obesity." (PMID 37440712, 2023). "S-calcium, S-25(OH)D (vitamin D), and S-PTH (parathyroid hormone) were measured in all persons with obesity at baseline and two years after treatment (n = 713)." (PMID 38134006, 2023). "In this study, we considered the effect of obesity on BMD, vitamin D and PTH levels and the risk of fracture in a group of postmenopausal women." (PMID 35789433, 2022). "This study focused on the plausible role of PTH in the prediction of NAFLD in patients with obesity following bariatric surgery." (PMID 35265372, 2022). "In contrast, other authors have not demonstrated a “J” curve for the relationship between 25OHD and PTH, suggesting that numerous other factors such as age, gender, degree of obesity, and ethnicity come into play in the steady state of 25OHD." (PMID 35893864, 2022). "A recent study, performed in a large population of children and adolescents to establish reference intervals for bone turnover markers, investigated the influence of obesity and pubertal status on the concentrations of bone markers, PTH and 25(OH)D." (PMID 34684321, 2021). "In fact, almost 90% of the subjects with obesity in this study belonged to the elevated PTH response group." (PMID 34580590, 2021). "As expected, we also observed that people with obesity exhibited higher PTH blood concentrations parallel to lower levels of 25(OH)D in order to maintain a normal calcium–phosphorus product." (PMID 34071985, 2021). "Recent evidence suggests that both obesity and low vitamin D levels are accompanied by significantly higher PTH levels, and high PTH levels are related to depression." (PMID 34847921, 2021). "PTH refers to rare clinical and endocrine manifestations like ectopic ossification, TSH resistance, GH deficiency, and early-onset obesity." (PMID 33299887, 2020). "That study suggests that obesity lowered vitamin D levels and elevated PTH together disturbed the balance in favour of the oxidant system." (PMID 33033457, 2020). "Frequently, PTH is elevated after obesity surgery, and long-term studies indicate that PTH increases over time." (PMID 32306297, 2020). "In fact, physiologic elevation of PTH levels has been postulated as an independent predictor of obesity." (PMID 32024097, 2020). "Only obesity (pre-pregnancy BMI ≥30), preterm birth and maternal blood parathyroid hormone concentration varied significantly across the chosen vitamin D cut-off points (p < 0.05)." (PMID 33114615, 2020).
Obesity (continued). "The aim of this study is to analyze the changes in vitamin D status and PTH levels in a group of children with obesity included in a combined dietary-behavioral-physical activity intervention program in order to get BMI status reduction." (PMID 31164629, 2019). "25(OH)D levels were significantly higher in the control group (P < 0.05), whereas the mean values for PTH levels were significantly higher in the obesity group (P < 0.05)." (PMID 31164629, 2019). "PTH concentrations were elevated in children with obesity in our study in concordance with most studies." (PMID 31164629, 2019). "Further, future trials should consider obesity when selecting an optimal vitamin D dose, as vitamin D was effective in reducing PTH levels only in normal weight subjects." (PMID 30934881, 2019). "On the other hand, patients with obesity exhibited mean PTH values significantly higher than subjects in normal BMI status, a fact that presumably would allow maintaining similar calcium levels in both groups, as we observe in this study." (PMID 31164629, 2019). "The aim of this work is to analyze the changes in vitamin D status and PTH levels in a group of children with obesity receiving combined intervention program in order to get BMI status reduction." (PMID 31164629, 2019). "The participants in this Consensus Statement agreed that the diagnosis of PHP should be based on major criteria, including resistance to PTH, ectopic ossifications, brachydactyly and early-onset obesity." (PMID 29959430, 2018). "Calcidiol levels were significantly higher in normal and overweight groups (P=0.001), whereas the mean values for PTH levels were significantly higher in obesity and severe obesity groups (P=0.001)." (PMID 28287628, 2017). "Calcidiol levels were significantly higher in normal and overweight groups (P=0.001), whereas PTH levels were significantly higher in obesity and severe obesity groups (P=0.001)." (PMID 28287628, 2017). "Vitamin D also affects obesity; low serum vitamin D levels always accompany increased serum parathyroid hormone levels and calcium influx of fat cells, which stimulates lipogenesis, inhibits fat decomposition, and aggravates obesity." (PMID 25741510, 2015). "Although Mexican American youth had a higher rate of LBW and obesity compared to Whites, they had little difference in PTH after adjusting for age, sex, birth weight and obesity." (PMID 26176843, 2015). "It has long been accepted that both depressed 25-(OH) D and reactive rises in PTH were consequences of obesity." (PMID 27275291, 2015). "The intervention between obesity, vitamin D and PTH is complex, suggesting possible effects at different levels." (PMID 24397367, 2014). "Maternal inheritance resulted in obesity and resistance to PTH and TSH whereas paternal inheritance lead to a minimal increase in adiposity and normal hormone responsiveness, mimicking the imprinting effects seen in PHP1A and PPHP." (PMID 23284784, 2012). "Retrospective study of all patients who had attended the obesity clinics in a Spanish hospital between 2009 and 2011, and whose concentrations of PTH, 25(OH)D, calcium and alkaline phosphatase had been determined (n=316, 75.9% women)." (PMID 23228198, 2012). "On the other hand, alterations in vitamin D metabolism and parathyroid hormone (PTH) concentrations are closely related to obesity as well as the clinical aspects of the metabolic syndrome." (PMID 22363895, 2012). "The obese are characterized by calciotropic hormones disturbances, including lower 25-hydroxyvitamin-D3 (25-OH-D3) and higher parathyroid hormone (PTH) serum concentrations, which increases along with the degree of obesity." (PMID 22164160, 2011). "As argued by McCarty & Thomas, validation of such a pathway would be important to obesity management, since there are other approaches to suppressing PTH, besides increasing dietary calcium." (PMID 22254043, 2010). "PTH has been proposed as a stand-alone predictor of obesity." (PMID 40585599, 2025).